TERT (telomerase reverse transcriptase)
Diseases named in the same sentence as TERT in open-access papers (continued):
Sharing a sentence is not in itself a finding about the gene and the disease.
meningioma (continued). "In this study, we analyzed data of patients who underwent meningioma surgery with neuropathologically assessed TERT promoter mutation status." (PMID 37686690, 2023). "In higher grade meningiomas, other genomic alterations with independent prognostic value have been reported, namely mutation of TERT promoter and deletions of CDKN2A/B." (PMID 37760490, 2023). "Recent studies have also illustrated the mutations in TERT promoter regions in grade III meningiomas, along with alterations in SMARCE1 and BAP1 that have been reported widely in clear cell and the rhabdoid subset of meningiomas." (PMID 37770851, 2023). "Identification of risk factors associated with TERT promotor mutations in meningiomas are urgently needed to enable systematic screening in selected patients." (PMID 37686690, 2023). "In our own series, we further demonstrated a para-sagittal tumor location as a strong predictor for TERT promotor mutations in high-grade meningiomas." (PMID 37686690, 2023). "Mutations in the telomerase reverse transcriptase (TERT) gene promoter are rare in meningiomas, but are associated with more aggressive forms of meningiomas as well as recurrence and progression." (PMID 37686690, 2023). "High neoantigen load in high grade meningioma presents the opportunity for immunologic therapy targeting TERT associated neoantigens." (PMID 37860270, 2023). "As such, the revised definition of anaplastic meningioma in the 2021 WHO Classification of Central Nervous System Tumors now includes any meningioma that harbors TERT promoter mutation or CDKN2A homozygous deletion." (PMID 36723772, 2023). "The presence of TERT promotor mutations is linked to poor prognosis, reduced time to progression and increased risk of malignant histopathological progression in meningioma." (PMID 37860270, 2023). "TERT promoter mutations in the hotspot regions C228T and C250T have been observed in 6.5% of meningiomas at diagnosis and 28% of those undergoing malignant histological progression." (PMID 36882706, 2023). "While the difference in RFS between grade 2 and 3 meningiomas was insignificant, a few conventional grade 2 cases, but with TERT promoter hotspot mutation, were highly progressive and refractory to the treatment." (PMID 35774130, 2022). "In line with this, the WHO 2021 grading has identified TERT-promotor mutated meningiomas as grade 3 tumors." (PMID 36291821, 2022). "Mutations in the chr5:1,295,228 (C228T) and chr5:1,295,250 (C250T) regions of the TERT promoter have been associated with uncontrolled proliferation in several cancers and recently in meningiomas that demonstrate histological malignant transformation." (PMID 36686824, 2022). "Another important finding is the different role played by TERT mutations in favoring the progression of meningioma." (PMID 35565385, 2022). "TERT promoter mutation, now adopted to molecular diagnosis of grade 3 meningioma, represented highly progressive tumors in our cases." (PMID 35774130, 2022). "Further, the incidence of TERT promotor mutations was shown to be higher in recurrent and higher grade meningiomas as well as associated with shorter progression‐free survival." (PMID 35213082, 2022). "TERT promoter mutations are important in atypical transformation of Grade 1 meningiomas, and are thus found in higher grade, malignant tumors, predicting increased recurrence risk." (PMID 34846640, 2022). "These mutations, found in ~ 6% of meningiomas, cause TERT upregulation, which abnormally extends the telomeres of meningioma cells, enhancing their lifespan." (PMID 34846640, 2022). "The TERT promoter hotspot mutation PCR was available for 52 cases (40 samples and additional 12 cases) with grade 2/3 meningiomas." (PMID 35774130, 2022).
meningioma (continued). "TERT promoter mutation was found to be key in meningiomas undergoing malignant histological progression and predictor for poor survival." (PMID 36033542, 2022). "TERT promoter mutations are more commonly seen in higher grade meningiomas, with mutations found in 1.7%, 5.7% and 20% of 2007 WHO classification grade 1, 2, and 3 meningiomas respectively." (PMID 36686824, 2022). "In a univariable analysis, meningiomas with TERT promoter mutation were associated with increased diameter and increased volume." (PMID 36497370, 2022). "Diffusion weighted imaging (DWI) parameters correlate with TERT promoter mutation status in grade 2 meningiomas." (PMID 36497370, 2022). "TERT promoter mutations are found in 6.4% of all meningiomas and are associated with higher grade tumors with 1.7%, 5.7%, and 20% of tumors making up grade I, II, and III, respectively." (PMID 33801089, 2021). "TERT promoter mutations have been found in about 6% of adult meningiomas and were associated with higher meningioma grade and early recurrence." (PMID 34495383, 2021). "In higher grade meningiomas, mutations of TERT promoter and deletion of CDKN2A/B seem to have a prognostic value." (PMID 34679551, 2021). "While 6% of meningiomas possess TERT promoter mutations, nearly 80% of TERT mutations in meningioma co-occur with NF2 mutations and are associated with higher tumor grade and significantly decreased tumor-free progression." (PMID 33445724, 2021). "Several studies have shown that TERT promoter mutation in meningiomas is associated with worse prognosis and shorter overall survival independent of WHO grade." (PMID 34679551, 2021). "Several studies have provided evidence that TERT-alt mutations are associated with rapid recurrence and malignant progression in meningioma." (PMID 34778063, 2021). "TERT alterations, specifically TERT promoter mutations, have been identified in a subset of HGMs with progression from low-grade meningioma." (PMID 34778063, 2021). "As a result it is unlikely that TERT promotor mutations have value in the prediction of meningioma WHO grade I regrowth after GKRS in the current study." (PMID 34385566, 2021). "Epigenetic modification on the level of histones, namely the loss of H3K27me3, as well as TERT promoter mutation were associated with increased risk of meningioma recurrence." (PMID 33053798, 2020). "Hotspot mutations in the TERT promoter were found in 20% of WHO grade III meningiomas (1.7 and 5.7% in WHO grade I and II meningiomas, respectively) and are associated with unfavorable outcome." (PMID 32676456, 2020). "In vitro, TERT mutated meningioma cells show decreased TERT activity in response to YK-4-279, a small molecule inhibitor of ETS transcription factor, suggesting a novel potential strategy for targeting these aggressive tumors." (PMID 31970090, 2019). "Recently, telomerase reverse transcriptase (TERT) mutations in the promoter region were discovered in meningiomas." (PMID 31470906, 2019). "To date, loss of the chromosomal region 1p and mutations in SMO, AKT1 and the TERT-promoter are known as independent predictors for meningioma recurrence." (PMID 31139260, 2019). "More recently, TERT promoter mutations have been reported in ~6% of all meningiomas, with ~80% of these also harboring alterations (mutations or deletions) at the NF2 locus." (PMID 31970090, 2019). "Meningiomas with mutations of the TERT-promoter are associated with shorter time to progression and a higher risk of recurrence." (PMID 31139260, 2019). "In grade I meningioma, TERT C228T and C250T mutations are linked with transformation to higher grades, prompting many scientists and clinicians to consider standardized testing for these specific changes." (PMID 31970090, 2019). "To date, loss of the chromosomal region 1p and mutations in SMO, AKT1 and the TERT promoter are independent (cyto-)genetic predictors for meningioma recurrence." (PMID 31139260, 2019).
meningioma (continued). "TERT promoter mutations in the hotspot regions C228T and C250T are observed in about 6.5% patients at diagnosis and in 28% of patients with meningioma undergoing malignant histological progression." (PMID 30279357, 2018). "Patients with meningioma with TERT mutations have shorter survival time and time to progression after treatment, suggesting the role of TERT promoter mutation in tumor evolution and progression." (PMID 30082628, 2018). "TERT gene (5p15.33) promoter mutations are often identified in meningioma and are associated with recurrence and malignant progression." (PMID 30082628, 2018). "Mutations in the TERT promoter and increased TERT mRNA expression were recently reported in a subset of meningioma that recur and undergo malignant progression." (PMID 25347344, 2014). "Furthermore, as the first reported case of an intraspinal chordoid meningioma progressing to an anaplastic meningioma with TERT mutation, this finding reveals the biological diversity of this subtype." (PMID 41013491, 2025). "Oncogenic TERT promoter variants, though rare, have been reported in lower-grade meningiomas." (PMID 40951339, 2025). "This case confirms that chordoid meningiomas can undergo malignant progression to CNS WHO grade 3 anaplastic meningiomas driven by TERT promoter mutations, challenging the traditional perception that chordoid meningiomas exhibit relatively indolent biological behavior." (PMID 41013491, 2025). "Consequently, the 2021 WHO Classification of Tumors of the CNS stipulates that meningiomas with a TERT promoter mutation should be classified as WHO grade 3." (PMID 41013491, 2025). "Besides 1p deletion, losses of chromosome 6q, 10, 17q and 18q, mutations of the TERT promoter or homozygous deletions of CDKN2A/B are described to influence the clinical course in meningioma patients." (PMID 39775316, 2025). "In addition, the presence of CDKN2A/B gene deletion or a TERT promoter mutation was added as a criterion for Grade 3 meningioma in the 2021 CNS WHO classification." (PMID 40356449, 2025). "Interestingly, the FOXM1 and E2F transcriptional pathways have been found to underlie de novo formation of atypical meningiomas, while progressing meningiomas harbor TERT promotor mutations." (PMID 38730704, 2024). "On a cautionary note, sample sizes of patients with histologically and molecularly more aggressive meningioma (WHO grade 3, TERT promotor mutated) were small, limiting the model’s usefulness in evaluating the effect of more aggressive meningiomas on the risk of preoperative seizures." (PMID 38581569, 2024). "The update in 2021 included molecular factors that significantly shorten survival and increase recurrence, such as meningiomas with a telomerase reverse transcriptase (TERT) promoter mutation or homozygous deletions in the cell cycle regulator genes CDKN2A and/or CDKN2B." (PMID 39796674, 2024). "Grade 2 meningioma patients treated at our institution were re-classified using an integrated risk stratification involving DNA methylation array-based data, copy number assessment and TERT promoter mutation analyses." (PMID 38720399, 2024). "We identified two patients with meningiomas with TERT promoter mutations." (PMID 36882706, 2023). "Considering their impact on meningioma grading and therapy, their low frequency, and the corresponding need for targeted screening analyses, we therefore analyzed the value of radiomics to predict TERT promoter mutations in series of intracranial high-grade meningiomas." (PMID 37686690, 2023). "Similarly, TERT promotor mutation associated with histopathological progression allows for prospective targeting of low-grade meningioma with this mutation using aggressive TERT immunologic therapy." (PMID 37860270, 2023).
meningioma (continued). "Hence, as the first study so far, we here demonstrate the capability of radiomics to predict TERT promotor mutations in high-grade meningiomas in routine preoperative imaging, with considerable reliability according to Cohen’s Kappa analyses." (PMID 37686690, 2023). "Hence, other characteristics, such as mutations of the TERT promoter, will have to be investigated in irregularly shaped meningiomas to further understand the molecular pathophysiology of meningioma shape." (PMID 37370707, 2023). "Moreover, according to the fifth edition, any meningioma with TERT promoter mutation and/or CDKN2A/B homozygous deletion is considered grade 3." (PMID 37760490, 2023). "A TERT promoter variant was detected in two patients (A, B), both with convexity meningiomas." (PMID 36882706, 2023). "Therefore, anaplastic meningiomas are now diagnosed if TERT promoter mutations and/or CDKN2A/B homozygous deletion occur, even in the absence of histological features consistent with anaplasia." (PMID 36661712, 2023). "Furthermore, a meningioma harboring either a TERT promotor mutation or homozygous deletion of CDKN2A/B is classified as a grade 3 anaplastic tumor, regardless of histologic grade." (PMID 35402234, 2022). "TERT mutations occurred more frequently in NF2 wild-type meningiomas." (PMID 35299730, 2022). "TERT promoter mutations are now included in the 2021 WHO classification of grade 3 meningiomas." (PMID 36686824, 2022). "Other studies demonstrated that the integration of the histopathological diagnosis with the methylation profile, karyotype, or mutational status of the TERT promoter could allow for a better prognostic stratification of meningiomas." (PMID 33670055, 2021). "Also, other molecular and epigenetic markers in meningioma such as TERT promoter mutation, loss of histone methylation, as well as complex methylation signatures have been very recently associated with early meningioma recurrence and progression." (PMID 33674888, 2021). "We therefore conducted a TERT promoter status analysis in our study cohort, hypothesizing that TERT promoter mutation might link the other tumors and meningioma in our patients." (PMID 33674888, 2021). "Additionally, much higher mutation rates of TERT promoter is significantly associated with malignant progression of low grade meningiomas." (PMID 33425743, 2020). "Development of TERT inhibitors could have a large indication not only in meningioma but also in other cancers that harbor TERT promoter mutation by reversing the phenotype cancer acquires with hyperactive TERT." (PMID 30082628, 2018). "It is possible that other known cancer-specific mechanisms of telomere maintenance such as ATRX/DAXX mutations or TERT rearrangements could be present in meningiomas." (PMID 29312603, 2017). "In addition to the TERTp mutations, we identified for the first time in meningioma a fusion that involves the TERT gene (LPCAT1:TERT)." (PMID 29312603, 2017). "In addition, TERT promoter (TERTp) variants have been associated with a shorter time to progression in meningiomas and have been included as an independent criterion for WHO grade 3 meningiomas in the 2021 WHO Classifications of Tumors of the Central Nervous System." (PMID 35804955, 2022). "In addition, although our NGS panel enables a broad survey of known cancer genes, it does not screen for relevant genomic alterations such as DMD deletions or TERT gene translocations both of which have been shown to be associated with a poor outcome in progressive/high-grade meningiomas." (PMID 33087175, 2020). "These estimates must be tempered as the frequency of TERTp mutations might be underestimated in high-grade meningiomas due to intratumoral heterogeneity, the late emergence during tumor evolution, or the occurrence of other TERT alterations, such as gene rearrangements." (PMID 33087175, 2020).
meningioma (continued). "The mutation rates of the TERT promoter and CDKN2A/B in meningiomas are typically less than 5% and are often co-occurring with Neurofibromin 2 (NF2) mutations and/or 22q chromosome deletions." (PMID 40502635, 2025). "Homozygous deletions of CDKN2A/B and oncogenic TERT promoter mutations are well-established independent adverse prognostic factors and defining features of CNS WHO grade 3 meningiomas." (PMID 40951339, 2025). "In this study, homozygous CDKN2A/B loss was observed in a single grade 3 meningioma, while all histologically low-grade tumors retained intact CDKN2A/B and TERT loci." (PMID 40951339, 2025). "The 2021 WHO Classification of CNS Tumors incorporates molecular criteria, including CDKN2A homozygous deletion and TERT promoter mutation, in the diagnosis of anaplastic (WHO grade 3) meningioma." (PMID 41497451, 2025). "Again, only presence of edema remained an independent risk factor for preoperative seizures in patients with meningioma WHO grade 2 or 3 and available TERT promotor mutation status (OR 6.61, 95%-CI 1.18, 58.12, *p = 0.049, Suppl." (PMID 38581569, 2024). "FD is caused by a mosaic activating pathogenic variant in GNAS gene, and the development of sporadic meningiomas also has genetic predisposition including NF2, TRAF7, KLF4, AKT1 and TERT." (PMID 38287340, 2024). "One of the first benign meningioma cell lines, Ben-Men-1, was derived from a CNS WHO grade 1 meningioma by transducing tumor cells with the human TERT gene to overcome cellular senescence." (PMID 38695575, 2024). "TERT promoter mutations or homozygous deletion of cyclin-dependent kinase inhibitors A and B (CDKN2A/B) are molecular features of grade 3 meningiomas." (PMID 39202270, 2024). "This genetic subset is more likely to progress to a higher WHO grade given its increased propensity to develop TERT promotor mutations and CDK2NA/B deletions, as is now reflected in the updated WHO definition of grade 3 meningiomas." (PMID 38611105, 2024). "The presence of TERT promoter region mutations and CDKN2A/B homozygous deletion are now diagnostic of grade 3 meningioma." (PMID 37860270, 2023). "NF2, TERT, SMARCB1, SMARCE1 and BAP1 have been associated with higher grade meningioma and poor prognosis." (PMID 36882706, 2023). "On the other hand, a proportion of meningiomas contain germline mutations of BAP1, SMARCB1, and SMARCE112, 13, 14, 15; mutations affecting the TERT promoter or altered methylation patterns appear to be associated with more aggressive behavior." (PMID 37366279, 2023). "Additional TERT promoter mutation and homozygous CDKN2A/B loss have similarly been linked to more aggressive meningiomas In contrast, homozygous CDKN2A/B loss, TERT promoter mutations or alterations in BAP1 are associated with more aggressive clinical courses." (PMID 36641486, 2023). "Relatively few gene-level alterations, including CDKN2A/B, TERT, and NDRG2 (N-myc downstream-regulated gene family member 2), have been strongly associated with the malignant progression of meningioma." (PMID 36836440, 2023). "Mutations in SMARCE1, BAP1, KLF4/TRAF7, TERT promoter, and CDKN2A/B deletion, H3K27me3 loss and methylation profiling are now officially associated with the classification and grading of meningiomas." (PMID 34846640, 2022). "Among the various molecular players that have been investigated, TERT has been proposed as a useful tool for meningioma grading; in fact, the rate of telomerase hyperactivity increases in higher grades." (PMID 36232992, 2022). "Meningioma‐relevant mutations were present in 90/126 (71.4%) specimens including NF2, TRAF7, KLF4, SMO, AKT1,TERT promotor, ARID,SUFU, and PIK3CA mutations in similar frequencies compared to previous studies." (PMID 35213082, 2022). "To evaluate the clinicopathologic relevance regarding the molecular diagnostic criteria in WHO CNS 5, we assessed the TERT promoter and CDKN2A/B status of meningioma." (PMID 35774130, 2022).